CRP (C-reactive protein)
Diseases named in the same sentence as CRP in open-access papers (continued):
Sharing a sentence is not in itself a finding about the gene and the disease.
Sepsis (continued). "Nevertheless, in the present study, the levels of CRP, PCT and TPO upon admission to the ICU were higher in patients who deteriorated compared to those who improved only in the group of patients with severe sepsis with sufficient predictive value (AUROCs 0.73–0.75)." (PMID 33917002, 2021). "As secondary outcomes, we investigated whether or not CPD may correlate at t0 with CRP, patient survival, and severity of sepsis course." (PMID 33777867, 2021). "Also CRP differed for patients with and without sepsis (109.29 ± 32.21 mg/L versus 82.54±38.13 mg/L)." (PMID 34324506, 2021). "However, CRP, PCT, and ALB levels, 14-day mortality rates, and sepsis-associated coagulopathy would not be affected by the judgments of physicians." (PMID 32778146, 2020). "Multiple linear regression analysis was employed to evaluate the relationship between SOFA scores and confounding factors that may be related to the severity of sepsis, including miR-223, age, lymphocyte counts, monocyte counts, white blood cell (WBC) counts, PCT, CRP, IL-6, and D-dimer." (PMID 33077816, 2020). "In addition, the concentrations of C-reactive protein (CRP) and procalcitonin (PCT) were determined to evaluate whether these biomarkers can provide criteria for performing REBA Sepsis-ID in clinical settings." (PMID 32850901, 2020). "Though CRP may indicate likelihood for sepsis, PRISMS did not recommend its use for patients with danger signs." (PMID 32854664, 2020). "In this study, three cases with proven sepsis had a negative CRP." (PMID 32238170, 2020). "Additionally, delta change percentage (dC%) between improved sepsis neonates and sepsis neonates without improvement showed a significant difference in the levels of both nCD64 (P < 0.001) and hs-CRP (P = 0.001)." (PMID 32832553, 2020). "We compared vital signs, PaO2/FIO2, serum C-reactive protein (CRP) levels, acute physiology and chronic health evaluation (APACHE) II score, sequential organ failure assessment (SOFA) score, and uNGAL levels between the sepsis group and the esophagectomy group." (PMID 31988752, 2020). "When the diagnosis of sepsis is already established (which occurs mainly in general wards), eqSOFA2+CRP+MR-proADM should be used in place of eqSOFA1, to rule out patients at high risk of mortality with the same high predictivity exhibited by eqSOFA1 in undifferentiated patients." (PMID 32331426, 2020). "These patients had also a longer duration of symptoms (P = 0.04), higher temperature (P = 0.03), more extensive cellulitis (P = 0.02), higher leukocyte (P < 0.0001) and neutrophil (P < 0.0001) counts, serum creatinine (P = 0.001), and CRP (P = 0.008) than patients without sepsis." (PMID 32164590, 2020). "Receiver operating characteristics (ROC) analyses were used by analysing the area under the curve (AUC), specificity, sensitivity, positive predictive value (PPV), negative predictive value (NPV) of the CRP taking the blood culture as the gold standard of neonatal sepsis diagnosis." (PMID 32238170, 2020). "However, inflammatory markers (leukocyte count and CRP level) and serum creatinine did not significantly differ between sepsis and non-sepsis groups (p = 0.073, p = 0.586, and p = 0.058, respectively)." (PMID 32160878, 2020). "CRP and PCT have been reported to be highly associated with infection likelihood, sepsis severity, and septicemia, but due to low specificity, they should not be used as the only criterion when diagnosing sepsis." (PMID 31964768, 2020). "PCT, similar to CRP, may be more useful to rule out sepsis than to diagnose it, and the combination of these two biomarkers may improve their ability to exclude sepsis." (PMID 32503670, 2020). "Six studies sought to assess whether the integration of qSOFA with plasma concentrations of conventional biomarkers of prognosis (C-reactive protein [CRP], lactate, and procalcitonin) could improve the performance of qSOFA alone in predicting sepsis outcome: however, the results were conflicting." (PMID 32331426, 2020).
Sepsis (continued). "CRP is a well-known inflammation marker, usually elevated in many inflammatory conditions, such as localized or organ infections, chronic rheumatic diseases, cancers, or coronary disease, but it is not considered to be specific for sepsis." (PMID 33374939, 2020). "However, CRP has low specificity for diagnosing sepsis, and the plasma level of CRP is not a reliable indicator for the degree of systemic inflammation." (PMID 31036824, 2019). "Compared with classical blood biomarkers of systemic inflammation (e.g., CRP), the proteins detected in this study, including haptoglobin, vWF, MBL1, MRC1, sCD14, and LBP, showed a very early response to infection, indicating their potential in serving as new early markers of infection or sepsis." (PMID 31803186, 2019). "CRP and ALB have been studied widely in various clinical settings and have been recognized as valuable prognostic markers for outcomes across various diseases, including sepsis, neoplasia, critical illness after intensive care unit (ICU) admission, and hospital-acquired acute kidney injury." (PMID 31821367, 2019). "Thus, extra care is necessary when using CRP and PCT as very early biomarkers for sepsis." (PMID 31470804, 2019). "Lnc‐THRIL relative expression was positively correlated with levels of CRP (r = 0.421, P < 0.001), PCT (r = 0.251, P = 0.008), TNF‐α (r = 0.357, P < 0.001), and IL‐1β (r = 0.305, P = 0.001), but not correlated with IL‐17 level (r = −0.072, P = 0.459) in sepsis patients." (PMID 31257645, 2019). "Additionally, several other diagnostic and prognostic biomarkers have been identified in sepsis, such as CRP, serum lactate, and IL-6, but the sensitivity or specificity is not high enough for enhancing the timely intervention of sepsis." (PMID 31771650, 2019). "Therefore, we performed the current study to determine whether the NLCR can be used to accurately establish a diagnosis of sepsis in ICU patients in comparison to WBC count, neutrophil count, lymphocyte count, CRP and PCT." (PMID 30811475, 2019). "Trauma or burn injury prior to death may increase IL-6 levels, and therefore the measurement of at least two postmortem CRP values seems to be warranted in order to identify sepsis-related fatalities when no anamnesis is available." (PMID 31661804, 2019). "The AUC of IL-6 to discriminate sepsis from the control group was 0.89 (95% confidence interval [CI], 0.97–1.00; P < 0.001), 0.84 for PTX3 (95% CI, 0.95–0.99; P < 0.001), 0.80 for PCT (95% CI, 0.86–0.96; P < 0.001), and 0.77 for CRP (95% CI, 0.71–0.91; P < 0.001)." (PMID 31718563, 2019). "Again, sepsis/bacteremia patients who arrived late into ED demonstrated significant increase in WBC count (18.70 ± 10.53 × 109/L versus 10.76 ± 4.08 × 109/L; p < 0.001) and CRP level (99.58 (43.92–182.30) mg/L versus 11.33 (6.11–23.40) mg/L; p < 0.001) when compared with viral group patients." (PMID 30974881, 2019). "Therefore, only one child had culture-positive sepsis although nine children had abnormal CRP levels (range 11–320 mg/l) and were managed as culture-negative sepsis." (PMID 31612119, 2019). "First, patients may have had high hs-CRP and sPDL1 levels before sepsis occurred rather than a consequence of sepsis." (PMID 31390038, 2019). "However, since PD patients have less severe sepsis than non-PD patients admitted to the ED, serum lactate levels were checked far less often in PD patients in the ED than CRP and differential white blood cell counts." (PMID 30417011, 2018). "Moreover, the number of sepsis discharges with no biomarker measurements fell significantly, and increased utilization was not seen for CRP." (PMID 30332466, 2018). "In adult intensive care unit (ICU) patients, resistin was superior to CRP in distinguishing sepsis from systemic inflammatory response (SIRS) due to trauma without infection, and the level of resistin was significantly higher in sepsis compared to trauma related SIRS." (PMID 30517161, 2018).
Sepsis (continued). "Measurement of serum P-SEP levels is valuable for the very early diagnosis of sepsis arising from bacterial or fungal infections because rises in P-SEP levels occur 12 to 48 hours earlier than rises are observed in the levels of other biomarkers (e.g., PCT and CRP)." (PMID 30647802, 2018). "However, in other studies, CRP levels alone did not successfully predict survival outcomes in patients with sepsis." (PMID 30297655, 2018). "Similarly, infants with sepsis, defined by elevated systemic markers of inflammation (IL-6 and/or CRP) and the use of antibiotics, showed a non-significant trend toward lower platelet counts before initiation of therapy." (PMID 29564323, 2018). "More than half of discharges (55%) with >1 PCT order had an extreme APR-DRG severity of illness score; 42% of discharges with 1 PCT, 40% of discharges with at least one CRP and/or lactate, and 25% of discharges with no-sepsis biomarker orders had an extreme APR-DRG severity of illness score." (PMID 30332466, 2018). "Thus, the C-reactive protein peak does not coincide exactly with the maximum temporal manifestation of sepsis but is close to it." (PMID 30202654, 2018). "Significant differences between the 169 episodes diagnosed as either severe bacterial sepsis or septic shock based on Sepsis-2 criteria and the 1,403 episodes that did not fulfil these criteria were found for all biomarkers (p < 0.001), except for CRP (p = 0.136)." (PMID 28727802, 2017). "However, in this specific population, the negative predictive value of PCT was lower than hs-CRP both in the diagnosis of sepsis and in septic shock." (PMID 28764651, 2017). "Noteworthy the CRP values did not correlate with either early- or late-onset sepsis." (PMID 28839172, 2017). "Despite their popularity, the consensus is that both PCT and CRP lack sensitivity and particularly lack specificity for sepsis, and further suffer from limitations such as PCT’s variable levels in early stages of sepsis—limiting its value to use in later stages of sepsis." (PMID 29104224, 2017). "Meanwhile, our study found that the concentration changes of plasma RIPK3 with time was similar to those of CRP levels, PCT levels, and SOFA score to monitor sepsis dynamically and then evaluate the severity of sepsis, which may be used for determining the prognosis of sepsis patients." (PMID 29137405, 2017). "However, when a clinical diagnosis of sepsis was suspected and CRP was negative, the antibiotic treatment was started." (PMID 27876013, 2016). "The rise of CRP or PCT from day 1 to day 3 in any patient group was evaluated as the expected peak serum levels related to the severity of infection rather than an ongoing uncontrolled sepsis." (PMID 26377840, 2016). "Comparative ROC-curve analysis on the predictive power for sepsis of TWEAK concentrations and other routine laboratory parameters revealed that TWEAK displayed superior or equal area AUC-statistics compared to leucocyte or PCT, but inferior AUC values compared to CRP." (PMID 27124414, 2016). "In patients with sepsis, we observed a strong positive correlation of chemerin with blood leucocyte count (p = 0.02) and thrombocyte count (p = 0.03), but not with C-reactive protein (CRP), interleukin-6 or glomerular filtration rate." (PMID 26873079, 2016). "The changes of CRP levels and hemogram parameters and their combinations may help to distinguish sepsis from non-sepsis SIRS at the ICU admission." (PMID 26863002, 2016). "In our study, we revealed lower CRP levels in the absence of co-infection or sepsis." (PMID 27017334, 2016). "However the specificity and sensitivity of current biomarkers, including C-reactive protein (CRP), Procalcitonin (PCT), and Interleukin-6 (IL-6) are limited in this setting, and recent studies have suggested the use of new biomarkers for sepsis, including analysis of circulating miRNAs." (PMID 26761003, 2016).
Sepsis (continued). "Rather than initial CRP concentrations, CRP concentrations measured a few days after admission may be more helpful for physicians to evaluate treatment response and sepsis outcome in the ICU." (PMID 26367532, 2015). "If sepsis is well controlled, PCT and CRP may show decreasing patterns." (PMID 26367532, 2015). "Nearly one-forth of neonatal bloodstream infections had a normal or low initial CRP level (<=10 mg/L), which was more likely to occur in low birth weight or extremely preterm infants, those with earlier onset of sepsis, and those infected with coagulase-negative Staphylococcus." (PMID 26259626, 2015). "C-reactive protein (CRP) and procalcitonin (PCT) are currently used as clinical indicators of inflammation and infection including bacteremia, and several other biochemical markers have been investigated for their ability to detect sepsis in an early, reversible phase." (PMID 25894539, 2015). "Based on our results, most variables commonly affecting C-reactive protein and procalcitonin values do not affect presepsin levels, which suggests that presepsin could be an effective sepsis marker." (PMID 26720209, 2015). "Despite extensive research in the past, only C-reactive protein (CRP), procalcitonin (PCT), and—to a lesser extent—interleukin (IL)-6 found their way into routine clinical use for assessment of the immune response in trauma-induced systemic inflammation and sepsis." (PMID 26607226, 2015). "Therefore, plasma CRP level should not be used to rule out severe culture-proven sepsis or guide the empirical choice of antibiotics." (PMID 26259626, 2015). "An optimal cut-off value of 2.2 μg/mL plasmatic calprotectin was identified to distinguish between infants with sepsis and infants without sepsis, with sensitivity and specificity of 62.5% and 69.7%, respectively, whereas CRP for a cut-off of 0.6 showed a sensitivity of 50% and specificity of 66.7%." (PMID 26380313, 2015). "When sepsis occurs, multiple redundant inflammatory cytokines are released into the blood stream, including tumor necrosis factor-α (TNF-α), interleukin-6 (IL-6), leptin, C-reactive protein (CRP) and procalcitonin (PCT), which are important for mediating the inflammatory response." (PMID 24669245, 2014). "PCT but not CRP (or the other markers) differentiates severe sepsis from septic shock." (PMID 24903083, 2014). "This suggests that specific macrophage-related biomarkers that reflect macrophage activation may indicate infectious inflammation in sepsis better than the non-specific CRP." (PMID 24637679, 2014). "C-reactive protein (CRP), tumor necrosis factor-α (TNF-α) and interleukins are among the first-discovered potential biomarkers for sepsis, among which IL-6 and IL-10 may be good choices as biomarkers while CRP and TNF-α are nonspecific biomarkers for inflammation." (PMID 24977412, 2014). "C-reactive protein (CRP), a kind of classical systemic inflammatory marker, was detected in this study to evaluate the ability of cytokines to eliminate sepsis and intracranial infection and to distinguish gram-negative bacteria (GNB) infection from gram-positive bacteria (GPB) infection." (PMID 24887408, 2014). "Finally, considering that PCT levels were not significantly different between patients without SIRS and patients with sepsis, CRP would be a more valuable marker of infection in those patients." (PMID 25407928, 2014). "As the clinical diagnosis of sepsis can be challenging and microbiological tests are unhelpful, several biomarkers have been developed to assist in the early diagnosis of sepsis, including procalcitonin (PCT), C-reactive protein (CRP) and, more recently, circulating cell-free DNA (cfDNA)." (PMID 25675360, 2014).
Sepsis (continued). "Multivariate linear regression analysis including APACHE-II score, SOFA score, CRP, white blood cells (WBC), creatinine, and platelet count as independent variables identified WBC (P <0.05, R2 = 0.64) and SOFA score (P <0.05, R2 = 0.64) as predictors for histone levels at onset of sepsis (day 1)." (PMID 25260379, 2014). "Single CRP in combination with RNSOS can be used for rapid identification of neonates with sepsis due to high sensitivity (95.6%) but cannot exclude those without sepsis due to low specificity (56.4%)." (PMID 25475836, 2014). "PTX3 in diagnosing sepsis does not appear to be superior to other biomarkers, like CRP and PCT." (PMID 25530683, 2014). "In contrast, sepsis did not modify the relationship between procalcitonin or C-reactive protein and brain dysfunction; thus, patients with higher biomarker levels had fewer delirium/coma-free days irrespective of whether they had sepsis or not." (PMID 24886875, 2014). "The second hypothesis may be that CRP and FGF21 are less specific, and are both increased in inflammatory states not linked to sepsis as opposed to PCT, which has been shown to be more specific for sepsis than CRP." (PMID 23999826, 2013). "Moreover, SAA can be combined with sICAM-1, CRP, and sE-selectin to improve the diagnosis results, and it can be also added to PCT and CRP, which may increase the rate of sepsis diagnosis by about 10%." (PMID 23984377, 2013). "As noted, the median PCT, but not CRP, level was determined to be significantly higher in patients with sepsis, severe sepsis or septic shock compared to the levels in patients with SIRS after the evaluation of patients according to criteria established by the ACCM/SCCM." (PMID 24330775, 2013). "In the present study, CRP identified 134 out of 181 neonates who had culture-proven sepsis, with sensitivity of 74.0% and a negative predictive value of 79.0%, implying that close to three quarters of neonates with suspected sepsis will be correctly diagnosed using CRP." (PMID 22958461, 2012). "This can be explained by the fact that levels of CRP may not have risen at the admission and sepsis is acquired later." (PMID 26023362, 2012). "Sepsis related with nosocomial infection, IMV application and the duration thereof, PaO2/FiO2, APACHE II on admission to ICU, SOFA scores (on admission to ICU and on the 3rd day), CRP values (initial, 3rd day, and ∆ CRP) were used to form a multi-logistical regression model." (PMID 23171626, 2012). "We assessed the relationship between the plasma concentrations of CRP, PCT, and PSP/reg; the concentrations of inflammatory cytokines; the number of leukocytes; severity scores (APACHE II, SAPS II and III, and SOFA); and in-hospital mortality in patients with severe sepsis or septic shock." (PMID 22748193, 2012). "They concluded that CRP was not an adequate test for the prognosis of sepsis patients." (PMID 23171626, 2012). "Therefore, a moderate re-increase in LBP or CRP plasma concentration in the second week of sepsis is no reliable indicator of a recurrent infection in this setting of postoperative sepsis." (PMID 21901123, 2011). "Furthermore, our results are consistent with studies that have shown an association of CRP with delirium in non-ICU cohorts, delirium following stroke and sepsis, and delirium in one small study of 32 ICU patients, which did not adjust for confounders." (PMID 21366899, 2011). "LBP, IL-6 and CRP levels were significantly higher among sepsis patients compared with infected children without SIRS (p < 0.001) and were significantly higher in the severe sepsis group compared with the less severe sepsis group (p < 0.001 for all differences)." (PMID 20158885, 2010). "In a recently published study, we also could not found a relation between CRP levels of the day of sepsis diagnosis and ICU survival." (PMID 20875120, 2010).